CD47 (CD47 molecule)
Diseases named in the same sentence as CD47 in open-access papers (continued):
Sharing a sentence is not in itself a finding about the gene and the disease.
ovarian carcinoma (continued). "Moreover, high level of CD47 is associated with poor prognosis in ovarian cancer, glioma, glioblastoma, and hematologic malignancies 9,12,13." (PMID 32226539, 2020). "In ovarian cancer, high CD47 expression is similarly correlated with poor clinical outcomes, primarily by suppressing macrophage phagocytic activity and promoting tumor immune evasion." (PMID 40396172, 2025). "Cox model and survival analysis manifested that high CD47 expression was an independent poor prognostic factor for ovarian cancer." (PMID 38832992, 2024). "The high CD47 expression was significantly correlated with the grade, lymph node metastasis and differentiation in ovarian cancer." (PMID 38832992, 2024). "By July 27, 2023, there were 95 clinical trials related to CD47, of which 35 were available for ovarian cancer patients." (PMID 38832992, 2024). "In this paper, we reviewed the biological roles of CD47 in ovarian cancer and summarized the related mechanisms." (PMID 38832992, 2024). "For example, the research pointed out that the expression level of CD47 was closely related to the immune infiltration of ovarian cancer, especially the positive correlation with the failure of Treg cells, monocytes, macrophages and T cells." (PMID 38832992, 2024). "In previous studies, immunohistochemical analysis presented that CD47 expression level in ovarian cancer tissues and borderline tumors was significantly higher than that in benign tumors and normal tissues." (PMID 38832992, 2024). "PLIC-1, which tethers to CD47 via its cytoplasmic tail and anchors vimentin filaments to the cell membrane, has been shown to promote the integrin-ανβ3-mediated spread of ovarian cancer cells." (PMID 39039207, 2024). "In the future, new immunotherapy regimens targeting CD47 can be applied to the clinical treatment of ovarian cancer patients." (PMID 38832992, 2024). "In a different study, anti-CD47 antibody (B6H12.2) increased macrophage infiltration in xenograft ovarian cancer cells and induced significant phagocytosis of OC stem cells." (PMID 38892394, 2024). "There were also indications in which the CD36/CD47 expression levels were consistent across all stages, such as Cervical cancer and Ovarian cancer." (PMID 39627379, 2024). "In treating ovarian cancer, the targets for PF-0725787, the dual checkpoint inhibiting BsAb, were CD47/SIRPα and PD-1/PD-L1 in order to maximize anti-tumor immunity." (PMID 38892394, 2024). "The relevance of targeting the TSP-1: CD47 axis in ovarian cancer was confirmed, enabling simultaneous targeting of different components of the ovarian microenvironment with a single molecule." (PMID 38832992, 2024). "Various approaches in treatment of ovarian cancer (OC) by targeting CD47-SIRPα axis are being researched in great numbers." (PMID 38892394, 2024). "The results revealed that the invasion of M2 and Tregs was higher in the ovarian cancer microenvironment with high CD47 expression level." (PMID 38832992, 2024). "Considering the clinical trials, which are currently exploring anti-CD47 antibodies against ovarian cancer, they aim to block this signal and enhance the immune system’s ability to eliminate cancer cells, offering a promising therapeutic strategy." (PMID 38892394, 2024). "In the realm of CD47 targeted therapy for ovarian cancer, various approaches have been explored, ranging from monotherapy inhibiting the CD47-SIRPα axis to combinations with tumor-targeting antibodies and bispecific antibodies disrupting the CD47-SIRPα axis." (PMID 39040441, 2024). "Further, we sought to assess the efficacy of targeting CD47 pathway alone and in combination in pre-clinical ovarian cancer (OC) models." (PMID 37468567, 2023). "Compared to control, CD47 blockade with SIRPa-Fc decoy receptor (TTI-621) enhanced macrophage-mediated in-vitro phagocytosis of ovarian cancer cells (OVCAR3 and TOV-21G)." (PMID 37468567, 2023).
ovarian carcinoma (continued). "We constructed CAR-Ms targeting HER2 and CD47 and verified their phagocytic ability to ovarian cancer cells in vivo and in vitro." (PMID 37740183, 2023). "After evaluating the successful repolarization into M1 macrophages, the macrophages were co-cultured for 4h with CD47+ ovarian cancer cell lines in the presence of an anti-CD47 mAb or isotype control mAb." (PMID 37876933, 2023). "We first examined the expression and localization of two oncogenes, HER2 and CD47, in tumor tissues of patients with ovarian cancer." (PMID 37740183, 2023). "In this study, we constructed CAR-Ms that target HER2 and CD47, respectively and investigated their ability to phagocytize ovarian cancer cells and activate adaptive immunity in vivo and in vitro." (PMID 37740183, 2023). "Taken together, the blockade of TIGIT induced a phenotypic repolarization defined by a reduction of M2-associated receptors and ultimately resulted in a significant augmentation of the anti-CD47-mediated ovarian cancer phagocytosis." (PMID 37876933, 2023). "A trend toward lower PFS was seen among those with high CD47 expression compared to lower CD47 expression both in the entire cohort and ovarian cancer sub-cohort." (PMID 37468567, 2023). "We examined the phagocytosis of HER2 CAR-M and CD47 CAR-M on ovarian cancer cells and the promotion of adaptive immunity." (PMID 37740183, 2023). "Then we assessed the activity of CD47 blockade therapy with SIRPa-Fc decoy receptor (TTI-621) using intraperitoneal (IP) xenograft ovarian cancer models with three ovarian cancer cell lines (TOV-21G, OVCAR3 and SKOV3)." (PMID 37468567, 2023). "Targeting CD47 has been shown to enhance macrophage phagocytosis and inhibit tumor growth in animal models of ovarian cancer, small cell lung cancer, breast cancer, and other cancers." (PMID 37720221, 2023). "Further, anti-CD47 significantly enhanced macrophage-mediated phagocytosis of ovarian cancer cells in-vitro." (PMID 37468567, 2023). "Anti-CD47 therapy showed evidence of up-regulation of markers of STING pathway especially when combined with Olaparib in ovarian cancer cells." (PMID 37468567, 2023). "Further, we investigated the activity of anti-CD47 therapy alone and in combination in preclinical models of ovarian cancer for potential future developmental strategy in combination approach." (PMID 37468567, 2023). "Given prior studies that reported synergy with cytotoxic agents, we then investigated the activity of anti-CD47 therapy combined with PARP inhibition compared to control and monotherapy both in-vitro and in-vivo in BRCA mutated ovarian cancer models." (PMID 37468567, 2023). "We investigated the activity of anti-CD47 with PARP inhibitors (PARPi) both in-vitro and in-vivo and noted synergistic effect with the combination in BRCA mutated ovarian cancer models." (PMID 37468567, 2023). "CD47 was highly expressed in the SKOV-3 (an ovary cancer cell line) and LS174T (a colorectal cancer cell line) cells." (PMID 36939440, 2023). "CD47 is a highly and ubiquitously expressed cell surface protein in ovarian cancer that induces cancer cell growth and predicts poor prognosis." (PMID 36352420, 2022). "Because CD47 is well-reported as having high expression on ovarian cancer cells but also on many healthy tissues, we designed a ΔCD47 CAR devoid of intracellular signaling domains to predispose cytotoxic impact on normal cells." (PMID 36059451, 2022). "In a phase I trial utilizing Hu5F9-G4, a CD47 antibody, 13 of 62 participants had advanced ovarian cancer." (PMID 35565348, 2022). "CPMV in situ vaccination combined with CD47-blocking antibody promoted macrophage activity and enhanced T cell function in ovarian cancer model." (PMID 36275669, 2022). "We tested this concept in a preclinical CAR study targeting ovarian cancer using TAG-72- truncated CD47 dual-targeting CAR-T cells (TAG-72 + ΔCD47 CAR-T)." (PMID 36059451, 2022).
ovarian carcinoma (continued). "In vitro studies exploring anti-CD47 therapy in ovarian cancer report the restoration of macrophage phagocytosis." (PMID 35565348, 2022). "To further explain correlation of CD47 with prognosis of ovarian cancer, we used several bioinformatics database including HPA, oncomine, GEPIA, Ualcan and KM plotter." (PMID 34966389, 2021). "Then, KEGG pathway enrichment was performed to explore the biological processes related to CD47 high expression in ovarian cancer." (PMID 34966389, 2021). "In OV_GSE115007 dataset, tumor ascites from primary ovarian cancer patients exhibited relatively low CD47 expression levels in plasma cells, dendritic cells and Mono/Macro cells compared to expression level in malignant cells of OV_GSE118828 dataset." (PMID 34966389, 2021). "Two independent datasets derived from oncomine showed that CD47 was highly expressed in ovarian cancer in Yoshihara Ovarian (P=3.66e-7) and Lu Ovarian (P=3.09e-8)." (PMID 34966389, 2021). "Close relation was found between CD47 expression level and immune infiltration in ovarian cancer, especially with Treg cells, Monocytes, Macrophages and T cell exhaustion (P<0.05)." (PMID 34966389, 2021). "We then evaluated correlation of T cell exhaustion biomarkers PD1 (PDCD1), CTLA4, LAG3 and HAVCR2 with the expression of CD47 in ovarian cancer." (PMID 34966389, 2021). "CD47 inhibits macrophage phagocytosis in ovarian cancer cells, and its downregulation or inhibition enhances the antitumor effect of macrophages." (PMID 35071016, 2021). "The results showed high CD47 expression in head and neck cancer, kidney cancer, myeloma, ovarian cancer, pancreatic cancer and sarcoma." (PMID 34966389, 2021). "This study aims to provide insights into prognosis and immune infiltration-related role of CD47 in ovarian cancer." (PMID 34966389, 2021). "The results showed that M2 and Tregs were increasingly infiltrated in high CD47 ovarian cancer microenvironment." (PMID 34966389, 2021). "Altogether, this round of data arising from multiple clinical data analyses establishes the relevance of targeting the TSP-1:CD47 axis in ovarian carcinoma." (PMID 34638503, 2021). "In OV_GSE118828 dataset, CD47 expression level remains the highest in malignant cells, suggesting high CD47 expression in malignant ovarian cancer cells." (PMID 34966389, 2021). "CD47 expression level was notably higher in ovarian cancer compared to normal ovarian tissues (P<0.05; num (T)=426; num (N)=88)." (PMID 34966389, 2021). "First, we used the HPA database to confirm CD47 expression in ovarian cancer and normal ovary tissue." (PMID 34966389, 2021). "M2 and Tregs were capable of making immunologic barriers against antitumor immune responses, indicating immune escape in CD47 high expression ovarian cancer." (PMID 34966389, 2021). "THBS1 mRNA expression levels also significantly correlate with poor prognosis for ovarian carcinoma patients, while both THBS1 and CD47 expression are associated with being decreased overall, as well as progression free survival." (PMID 34638503, 2021). "In the early 1990s, the first oncological studies of CD47 identified it as a potential tumor marker for ovarian cancer." (PMID 34944850, 2021). "The results showed that CD47 was highly expressed in ovarian cancer which was consistent with previous reports." (PMID 34966389, 2021). "KEGG and GSEA analysis indicated that CD47 high expression in ovarian cancer was mainly involved in toll-like receptor signaling pathway, NOD-like receptor signaling pathway, chemokine-signaling pathway and cytokine-cytokine receptor interaction pathways." (PMID 34966389, 2021). "A SIRPα‐Fc fusion protein enhances the antitumor effect of oncolytic adenovirus against CD47‐positive ovarian cancer." (PMID 31899582, 2020). "In vitro experiments have shown that phagocytosis by donor-derived macrophages is increased significantly against ovarian cancer patient cells treated with a CD24 mAb compared to CD47 mAb treatment and control." (PMID 32937961, 2020).
ovarian carcinoma (continued). "Its upregulation of expression on ovarian cancer cells compared to normal cells is greater than that for both CD47 and PD-L1, and is greatest for ovarian cancer when compared to numerous other cancers." (PMID 32937961, 2020). "A clinical trial with a mAb against CD47 (Hu5F9-G4) in combination with anti-PD-L1 (Avelumab) is currently underway for ovarian cancer patients who progressed within 6 months of prior platinum-based chemotherapy (NCT03558139)." (PMID 32937961, 2020). "Another (phase I trial; NCT03957096) that includes epithelial ovarian cancer patients, uses a CD47 antibody–drug conjugate (SGN-CD47M)." (PMID 32937961, 2020). "Enhanced expression of CD47 was observed in various types of cancers, such as lung cancer, ovarian cancer, and leukemia 9-11." (PMID 32226539, 2020). "The elevated expression of CD47 is found in many cancers, including gastric cancer, liver cancer, bladder cancer, lung cancer, ovarian cancer, lymphomas, and leukemia 8-11." (PMID 32226539, 2020). "Taken altogether, our results indicated that CD47 promotes ovarian cancer progression by inhibiting macrophage phagocytosis, and knockdown of CD47 or anti-CD47 mAb treatment can reverse this effect." (PMID 28380460, 2017). "We analyzed the CD47 expression profile in the tumor initiating cells of ovarian cancer to determine its role in immune escape." (PMID 28380460, 2017). "In this study, we confirmed the clinical significance of CD47 in ovarian cancer, showed the presence of CD47 dependency in anti-CD47 therapy, and investigated the possibility of using anti-CD47 mAb as a treatment paradigm." (PMID 28380460, 2017). "In this study, we confirmed that CD47 protein is highly expressed in ovarian cancer, and is correlated with poor clinical characteristics and prognosis." (PMID 28380460, 2017). "CD47 knockdown in the ovarian cancer cell line, SK-OV-3, promoted phagocytosis by macrophages in vitro and inhibited tumor growth in vivo." (PMID 28380460, 2017). "To further investigate the clinical significance of CD47 expression, we subdivided another cohort of 93 ovarian cancer patients based on their CD47 expression levels." (PMID 28380460, 2017). "Similar to the studies in glioma and ovarian cancer, we found that a higher CD47 mRNA level in osteosarcoma samples correlated with a poorer clinical outcome." (PMID 26093091, 2015). "Our results indicated that expression of CD47 was comparable to expression of CD44 in different ovarian cancer subtypes and displayed a positive correlation." (PMID 25658794, 2015). "CD47 has originally been reported to be overexpressed on the cell surface of ovarian cancer and investigated as a potentially broad cancer therapy target." (PMID 26318039, 2015). "Previous studies have investigated the expression of the three molecules individually in malignant ovarian tumors and have found that CD44 and c-met are highly expressed in OCCC, while CD47 is highly expressed in ovarian cancer tissues." (PMID 25658794, 2015). "CD47 has also been shown to be identical to the OA-3/OVTL3 antigen highly expressed on most ovarian carcinomas." (PMID 23401787, 2013). "CD47 is a cell surface marker that is broadly expressed in normal adult tissues and in human solid tumors including ovarian cancer." (PMID 24303006, 2013). "Furthermore, engineered approaches, such as CAR-macrophages targeting HER2 and CD47, have demonstrated efficacy in promoting phagocytosis of ovarian cancer cells and activating adaptive immunity." (PMID 41459510, 2025). "Notably, therapeutic blockade of CD47 has shown promising potential in enhancing macrophage-mediated phagocytosis of tumor cells, thereby inhibiting ovarian cancer progression." (PMID 40396172, 2025). "Indeed, both anti-CD47 monotherapy and the combined treatment of anti-CD47 with PARPi facilitate macrophage-mediated in-vitro phagocytosis, boost STING signaling, and eliminate tumor growth in BRCA-deficient ovarian cancer models." (PMID 40830526, 2025).
ovarian carcinoma (continued). "In terms of protein expression, we found that AXL was significantly up‐regulated in renal clear cell carcinoma, CD47 was significantly up‐regulated in ovarian cancer, pancreatic cancer and endometrial cancer, and MERTK was significantly up‐regulated in both ccRCC and pancreatic cancer." (PMID 40576208, 2025). "We found that AXL and MERTK were expressed at higher levels in liver tissue, lung tissue, endometrial tissue; CD47 was up‐regulated in breast tissue, lung tissue, ovarian cancer, pancreatic cancer and endometrial cancer; and HAVCR2 showed higher expression in renal clear cell carcinoma." (PMID 40576208, 2025). "As expected, we found that GA could promote M1-like macrophage polarization in ovarian cancer cells by reducing the CD47 expression in ovarian cancer cells." (PMID 40270598, 2025). "Notably, CD47 monoclonal antibodies and related molecules are promising in the immunotherapy of ovarian cancer, and further research is needed." (PMID 38832992, 2024). "Initially recognized for associating with the Rhesus (Rh) antigen complex on red blood cells (RBCs), subsequent early studies revealed that CD47 engages with ανβ3 integrin in human placenta and granulocytes and functions as an overexpressed tumor antigen in ovarian cancer." (PMID 39039207, 2024). "In ovarian cancer cell model, overexpression of CD47 significantly promoted migration and invasion." (PMID 38832992, 2024). "Moreover, upregulation of CD47 expression was associated with worse OS and progression free survival (PFS) in ovarian cancer." (PMID 38832992, 2024). "The results suggested that co-expression of TAG-72 CAR and CD47-truncated monomeric CAR on T cells may be an effective dual CAR-T cell strategy for the treatment of ovarian cancer." (PMID 38832992, 2024). "CD47 antagonists currently entering clinical trials for treatment of ovarian cancers." (PMID 39040441, 2024). "Tumors lacking CD24 expression have been found to be more sensitive to CD47 blockers, suggesting that simultaneous targeting of CD24 and CD47 may offer better clinical prospects for treating ovarian cancer." (PMID 39003350, 2024). "Blockage of CD47 shows also very promising results in therapy of ovarian cancer." (PMID 38892394, 2024). "This suggests that CD47 may play a role in making gynecologic cancers, including ovarian cancer, more resistant to immunotherapy treatments." (PMID 37468567, 2023). "CD47 expression was significantly elevated in patients who failed immunotherapy with immune checkpoint inhibitors in the entire cohort and similar pattern in ovarian cancer sub-cohort." (PMID 37468567, 2023). "Moreover, CD47 expression was also analyzed on primary spheroids derived from the MA (n=16) and tumoroids derived from primary tumor tissue (n=15) of ovarian cancer patients." (PMID 37876933, 2023). "Moreover, combined blockade of TIGIT and CD47 significantly increased phagocytosis of ovarian cancer cells by TAMs in comparison to a single blockade of CD47." (PMID 37876933, 2023). "The OAW42, SKOV3, and OvCar3 ovarian cancer cells highly express CD47." (PMID 37876933, 2023). "Moreover, a recent study sought to improve therapeutic efficacy safety for ovarian cancer by engineered an oncolytic herpesvirus to express anti-CD47 antibodies in tumors." (PMID 36650558, 2023). "Ovarian cancer cells were treated with anti-CD47 (Hu-5F9), Olaparib or both." (PMID 37468567, 2023). "We then investigated the activity of anti-CD47 in in-vivo xenograft models of ovarian cancer." (PMID 37468567, 2023). "We demonstrated the inhibition effect of our constructed novel HER2 CAR-M and CD47 CAR-M on target antigen-positive ovarian cancer in vitro and in vivo, and preliminarily verified that this inhibitory effect is due to phagocytosis, promotion of adaptive immunity and effect on tumor microenvironment." (PMID 37740183, 2023). "Therefore, we then investigated the activity of anti-CD47 therapy both in-vitro and in-vivo in ovarian cancer models." (PMID 37468567, 2023).